MALAT1 (metastasis associated lung adenocarcinoma transcript 1)
Diseases named in the same sentence as MALAT1 in open-access papers (continued):
Sharing a sentence is not in itself a finding about the gene and the disease.
non-small cell lung carcinoma (continued). "MALAT1 is a long intergenic ncRNA encoded on chromosome 11q13.1 with a length of more than 8.0 kb and was initially shown to be associated with the metastasis of non-small cell lung cell cancer (NSCLC)." (PMID 35954272, 2022). "In this manner this group demonstrated the detection of long non-coding RNAs (lncRNAs)—specifically metastasis-associated lung adenocarcinoma transcript 1 (MALAT1), a biomarker for non-small cell lung cancer—using differential pulse voltammetry to a detection limit of 42.8 fM." (PMID 34940243, 2021). "MALAT-1 was initially recognized as a metastasis-associated gene that might predict the potential metastasis of non-small-cell lung cancer." (PMID 32700729, 2020). "LncRNA metastasis-associated lung adenocarcinoma transcript 1 (MALAT-1) can be used to predict whether patients with non-small cell lung cancer (NSCLC) are at high risk of developing metastasis." (PMID 27429196, 2016). "Likewise, the long noncoding RNA MALAT1 is over-expressed in metastatic human lung, liver and colorectal cancer tissues, and a high level of MALAT1 expression is associated with poor prognosis in patients with non-small cell lung cancer." (PMID 24742640, 2014). "Moreover, long ncRNA MALAT1 (metastasis-associated lung adenocarcinoma transcript 1) was shown to be significantly associated with metastasis in non-small cell lung cancer patients." (PMID 23087702, 2012). "MALAT1, which stands for metastasis-associated lung adenocarcinoma transcript 1, is a long noncoding RNA that was initially discovered to may be overexpressed in tissues of non-small-cell lung cancer patients with a high propensity to metastasize?" (PMID 39512820, 2024). "MALAT1 is a long non-coding RNA that is significantly upregulated in non-small cell lung cancer (NSCLC) cell lines such as A549, H23, H522, H1299, and H460 when compared to normal bronchial epithelial cells." (PMID 41439968, 2025). "Metastasis-associated lung adenocarcinoma transcript 1 (MALAT1) significantly upregulates MRP1 and MDR1 by activating STAT3 in cisplatin (DDP) resistant non-small cell lung cancer." (PMID 41145465, 2025). "MALAT-1 was initially identified in 2003 during investigations into the metastasis of early-stage non-small cell lung cancer (NSCLC)." (PMID 39196297, 2024). "MALAT1 was also highly expressed in other various cancers like non-small cell lung cancer and melanoma, which is involved in a wide range of biological and cellular processes, including glycolysis and vascular growth, for promoting tumor progression." (PMID 38561330, 2024). "Circulating MALAT1 has been studied as a biomarker for non-small cell lung cancer, epithelial ovarian cancer, hepatocellular carcinoma and tongue squamous carcinoma, though its association with depression is not yet known." (PMID 38338752, 2024). "LncRNA MALAT1 initially identified in non-small cell lung cancer, is a lncRNA transcribed from the nuclear-enriched transcript 2 (NEAT2) gene." (PMID 38961978, 2024). "A lncRNA called MALAT-1 that is expressed from chromosome 11q13 was initially discovered to be overexpressed in non-small cell lung cancer." (PMID 38294554, 2024). "Metastasis-associated lung adenocarcinoma transcript 1 (MALAT1) is one of the most thoroughly studied LncRNAs, which was first recognized in 2003 as a prognostic factor for the survival of stage I non-small cell lung cancer patients." (PMID 39768369, 2024). "For example, MALAT1 (or NEAT2) is upregulated in non-small-cell lung cancer and can be used as a biomarker for early cancer prognosis, and the use of lncRNA HOTAIR has been explored as a potential biomarker for detecting recurrence of hepatocellular carcinoma." (PMID 37205123, 2023). "MALAT-1 was initially identified in patients with non-small cell lung cancer (NSCLC), and subsequent investigations revealed its upregulation in tumors displaying a pronounced metastatic potential." (PMID 38124072, 2023).
non-small cell lung carcinoma (continued). "Patient-derived datasets of melanoma, hepatocellular carcinoma, non-small cell lung cancer, and their respective adjacent healthy tissue controls have been previously used to show cancer-specific MALAT1-upregulation." (PMID 37235843, 2023). "In relation to lung cancer, TDP-43 has been found to enhance the metastasis of non-small cell lung cancer cells (NSCLC) through its regulation of MALAT1 expression." (PMID 37996849, 2023). "MALAT1 is also known as nuclear-enriched abundant transcript 2 (NEAT2, originally described to be associated with non-small cell lung cancer." (PMID 37250901, 2023). "Metastasis associated lung adenocarcinoma transcript 1 (MALAT1) is a well-known lncRNA and was originally discovered in non-small cell lung cancer." (PMID 36813772, 2023). "High expression of lncRNA MALAT1 in non-small cell lung cancer accelerated tumorigenesis via adsorbing miRNA-515-5p and then upregulating EEF2 protein levels." (PMID 37612724, 2023). "lncRNA MALAT1 aggravates the progression of non-small cell lung cancer by stimulating COMMD8 expression by targeting miRNA-613, and the tumorigenicity of MALAT1 has been verified in vivo." (PMID 35706002, 2022). "METTL3 promoted yes-associated protein (YAP) mRNA translation through YTHDF1/3 and eIF3B, and increased the stability of YAP mRNA by regulating the MALAT1/miR-1914-3p/YAP axis to induce non-small cell lung cancer (NSCLC) treatment metastasis and resistance b." (PMID 35711459, 2022). "MALAT1 is dysregulated in many cancers, including non-small cell lung cancer and modulates cell proliferation, apoptosis, migration, and invasion." (PMID 35630580, 2022). "METTL3 promoted YAP translation by recruiting YTHDF1/3 and eIF3b, and increased YAP expression by the MALAT1/miR-1914-3p axis, leading to drug resistance and metastasis in non-small-cell lung carcinoma (NSCLC)." (PMID 35164788, 2022). "High expression of MALAT1 promoted the progression of non-small cell lung cancer through the ERK / MAPK signaling pathway." (PMID 35928715, 2022). "Initially, MALAT1 was identified as a prognostic factor for early-stage non-small cell lung cancer metastasis; subsequent studies found that MALAT1overexpression was associated with poor outcomes in various cancers." (PMID 35558512, 2022). "Various studies have shown that MALAT1 exerts tumor-promoting effects in several cancers, including non-small cell lung cancer, osteosarcoma, cervical cancer, and pancreatic cancer." (PMID 35585970, 2022). "MALAT1 was initially identified as being up-regulated in primary human non-small cell lung cancer cells with higher metastasis ability, and was associated with metastasis and survival of cancer cells." (PMID 34012919, 2021). "MALAT1 can also be used to predict metastasis and survival in patients with early-stage non-small-cell lung cancer." (PMID 33728343, 2021). "MALAT1, located on chromosome 11q13 and especially on nuclear speckles, was initially identified as a prognostic marker in non-small-cell lung cancer (NSCLC)." (PMID 34202021, 2021). "It has been found that miR-124 is a negative regulator of osteoclastic differentiation, and the long non-coding RNA MALAT-1 (LncRNA-MALAT1) interferes with the miR-124 binding site on the integrin subunit β1 in non-small cell lung cancer." (PMID 34203627, 2021). "MALAT1 was identified as a prognostic biomarker that promotes cell proliferation and metastasis in non-small cell lung cancer (NSCLC) and other cancers." (PMID 33526059, 2021). "Initially, MALAT1 was identified as being up-regulated in primary human non-small cell lung cancer cells with heightened metastatic potential." (PMID 34012919, 2021). "Metastasis-associated lung adenocarcinoma transcript 1 (MALAT1), located on 11q13 in humans, is an lncRNA originally identified as a prognostic marker in non-small-cell lung cancer (NSCLC)." (PMID 34574033, 2021).
non-small cell lung carcinoma (continued). "For example, MALAT1 derived from exosomes has been found to be highly expressed in the serum of patients with non-small cell lung cancer, which can accelerate tumor migration and promote its growth." (PMID 34497634, 2021). "The expression of MALAT1 is upregulated in Non Small Cell Lung Cancer (NSCLC) and ovarian cancer metastatic tumors, promotes aggressive phenotypes, and can be used as a prognostic biomarker in stage I NSCLC." (PMID 32492865, 2020). "MALAT1, also known as Nuclear Enriched Abundant Transcript 2 (NEAT2) was first identified in a microarray screen of tumors from patients with non-small cell lung cancer, and was found to be upregulated in the tumors with a higher propensity to metastasize." (PMID 32503170, 2020). "MALAT-1, also referred to as noncoding nuclear-enriched abundant transcript 2, was initially identified to promote metastasis in non-small-cell lung cancer." (PMID 32700729, 2020). "The metastasis-associated lung adenocarcinoma transcript 1 (MALAT1), first identified in non-small cell lung cancer, is an 8,000 nucleotides lncRNA located in the chromosome 11q13.1." (PMID 32154165, 2020). "Metastasis associated lung adenocarcinoma transcript 1 (MALAT1) was first shown to contribute to metastasis and poor patient survival in non-small cell lung cancer (NSCLC) and later in the progression of TNBC." (PMID 32244924, 2020). "In non-small cell lung cancer cells, MALAT1 binds miR145-5p and decreases its expression, leading to increased NEDD9 protein expression, since miR145-5p targets the 3'-untranslated region (UTR) of NEDD9 mRNA." (PMID 32174966, 2020). "MALAT1 was firstly reported to be involved in the metastatic development in non-small cell lung cancer, and the role of MALAT1 in CRC attracted more attentions recently." (PMID 33005106, 2020). "A lot of lncRNAs, including MALAT1, HOTAIR, CCAT2, and AK126698, were found to be associated with non-small cell lung cancer (NSCLC) progression, metastasis, and invasion." (PMID 32607061, 2020). "The lncRNA metastasis-associated lung adenocarcinoma transcript 1 (MALAT1) significantly upregulates MRP1/ABCC1 and MDR1/ABCB1 by activating STAT3 in a cisplatin (DDP) resistant non-small cell lung cancer cells." (PMID 32164712, 2020). "MALAT1 is another important lncRNA, and in patients with non-small-cell lung cancer, it is significantly related to metastasis potential and poor prognosis." (PMID 32149133, 2020). "As a highly conserved nuclear noncoding RNA, MALAT1 was first described as tumor metastasis related gene in non-small cell lung cancer." (PMID 31995604, 2020). "Diosgenin exerts its tumor suppressive function to induce apoptosis by down-regulating MALAT1/STAT3 signaling in gefitinib-resistant non-small cell lung cancer." (PMID 31881805, 2019). "As example, targeting of MALAT1, a highly conserved lncRNA originally identified in metastatic non-small cell lung cancer, has shown promising results in cancer regression." (PMID 31382922, 2019). "It indicated that MALAT-1 in exosomes can be used as a noninvasive biomarker for diagnosis and prognosis of non-small cell lung cancer." (PMID 31133028, 2019). "LncRNA metastasis-associated lung adenocarcinoma transcript 1 (MALAT1), also known as nuclear-enriched transcript 2 (NEAT2), is discovered as a predictive marker for metastasis and survival in early-stage, non-small cell lung cancer." (PMID 31263681, 2019). "MALAT1 owes its name to its discovery as an overexpressed transcript in non-small cell lung cancer (NSCLC) metastases that provided an early-stage marker of NSCLC metastasis risk even before its molecular functions were characterized." (PMID 29685978, 2018). "Metastasis-associated-lung-adenocarcinoma-transcript-1 (MALAT-1) is a lncRNA that is overexpressed in multiple cancer cell lines and tumors, and MALAT-1 expression in early stage non-small cell lung cancer patients predicted patient survival and metastasis." (PMID 29389953, 2018).
non-small cell lung carcinoma (continued). "Metastasis Associated Lung Adenocarcinoma Transcript 1 (MALAT1), as one lncRNA, was first detected and highly expressed within non-small cell lung cancer (NSCLC)." (PMID 29368602, 2018). "MALAT1 was originally discovered in patients with non-small cell lung carcinoma and shortly after its discovery, MALAT1 has also been reported in various pathologies such as heart disease and diabetes." (PMID 29695738, 2018). "Although early reports provided evidence of its association with metastasis in early-stage non-small cell lung cancer (NSCLC) patients, subsequent studies reported that MALAT1 is extremely abundant and widely conserved among 33 mammalian species." (PMID 29739426, 2018). "Another lncRNA investigated in PCa is metastasis-associated lung adenocarcinoma transcript-1 (MALAT-1), originally known to be overexpressed in patients at high risk for non-small cell lung cancer metastasis, as its name implies." (PMID 29312884, 2017). "MALAT1 was originally identified as a prognostic marker for non-small cell lung cancer, and then was found upregulated in a range of tumor types." (PMID 28467811, 2017). "In a previous study, MALAT1 was reported as a potential complementary blood-based biomarker for the diagnosis of non-small cell lung cancer." (PMID 27999202, 2017). "The metastasis-associated lung adenocarcinoma transcript 1 (MALAT1), is located on the chromosome 11q13 and was firstly found as a predictive biomarker for metastasis in the early stage of non-small cell lung cancer." (PMID 29290978, 2017). "MALAT1 is also an independent prognostic marker for poor outcomes and patient survival in several cancer types, including stage I non-small cell lung cancer and hepatocellular carcinoma." (PMID 29156758, 2017). "Many lncRNAs are expressed in a tissue- and cancer-type-restricted manner and have already been shown to be useful as prognostic markers, such as HOTAIR in breast tumors and hepatocellular carcinomas, MALAT1 in non-small cell lung cancer." (PMID 26895099, 2016). "MALAT1 was first identified as an independent prognostic biomarker that can predict metastasis and survival in early stage non-small cell lung cancer (NSCLC)." (PMID 27527868, 2016). "Metastasis-associated lung adenocarcinoma transcript 1 (MALAT1), also known as nuclear-enriched transcript 2 (NEAT2), was first identified in the study of the metastasis of non-small cell lung cancer." (PMID 27564100, 2016). "For example, MALAT1 has been detected in the blood of patients with non-small cell lung cancer, and HOTAIR in colorectal cancer patients." (PMID 26516918, 2015). "Metastasis-associated lung adenocarcinoma transcript 1 (MALAT-1) has been described as a regulator of metastasis and motility, and its expression is associated with metastasis in non-small cell lung cancer." (PMID 25526029, 2014). "LncRNAs have been reported to be involved in cancer development in three different ways: Firstly, some lncRNAs take part in the process as oncogene or oncogene regulator, for example, MALAT1 gene in non-small cell lung cancer and H19 in colon cancer." (PMID 24330491, 2013). "Metastasis-associated lung adenocarcinoma transcript 1 (MALAT-1), which correlates with high metastasis and poor prognosis in non-small-cell lung cancer, is an abundant 8.7-kb lncRNA encoded in the human chromosome 11q13." (PMID 24036441, 2013). "Additionally, a new prognostic marker for patients with CRC has been described using the MALAT1, which functions as a predictive biomarker of metastasis in non-small cell lung cancer patients." (PMID 38294554, 2024). "MALAT1 was initially discovered as a prognostic marker in non-small cell lung cancer (NSCLC)." (PMID 38179937, 2024). "MALAT1, a molecule of intense investigation across various cancers, including lung, endometrial, breast, and invasieve cervical cancer, initially surfaced as a potential as a prognostic marker for non-small cell lung cancer metastasis." (PMID 37812599, 2023).
non-small cell lung carcinoma (continued). "MALAT1 was increased in non-small cell lung cancer due to METTL3-mediated high m6A modification." (PMID 37986103, 2023). "Non-small cell lung cancer patients were the ones who initially showed MALAT1 expression." (PMID 37919386, 2023). "MALAT1 is found to competitively bind to miR-200a-3p in non-small cell lung cancer." (PMID 36873948, 2023). "Additionally, increased MALAT1 expression has also been found to promote the proliferation, migration, and invasion of non-small cell lung cancer via the MAPK-signaling pathway." (PMID 37235843, 2023). "In this context, overexpression of the oncogenic lncRNA MALAT1 in non-small cell lung cancer (NSCLC) tissue is related to reduced overall survival and could be a potential prognostic biomarker and therapeutic target in early-stage lung cancer (LC)." (PMID 36866275, 2023). "Moreover, the lncRNA metastasis-associated lung adenocarcinoma transcript 1 (MALAT1), which acts as a predictive biomarker of metastasis in non-small cell lung cancer patients, has been described as a new prognostic marker in CRC patients." (PMID 36362222, 2022). "MALAT-1 was first discovered in a study of non-small cell lung cancer." (PMID 35928715, 2022). "MALAT1 was first identified in non-small cell lung cancer (NSCLC)." (PMID 36419933, 2022). "The expression of MALAT1 was first detected in patients with non-small cell lung cancer (NSCLC)." (PMID 35305641, 2022). "MALAT1 was firstly recognized in non-small-cell lung cancer." (PMID 35697671, 2022). "MALAT1 was first discovered as an imprinted gene in non-small cell lung cancer." (PMID 35635083, 2022). "One of the potential markers of stage 1 non-small cell lung cancer is the lncRNA MALAT1, which can be significantly down-regulated after resveratrol treatment, suggesting that resveratrol may be an entry point for the treatment of non-small cell carcinoma." (PMID 36686745, 2022). "A recent study performed by Wei and colleagues showed significant downregulation of miR-200a with an upregulation of MALAT1 lncRNA molecule in non-small cell lung cancer, which indicates that the MALAT1/miR200a/PD-L1 axis might have an important role in EMT." (PMID 35011635, 2021). "Moreover, this phenomenon was observed in non-small-cell lung cancer wherein the lncRNA MALAT1 was found to be protected by exosomes and involved in the promotion of distant metastasis." (PMID 34336125, 2021). "In addition, the lncRNA NEAT2 (also known as MALAT-1) was initially indicated as a prognostic indicator for early-stage non-small-cell lung cancer." (PMID 34830370, 2021). "In addition, in non-small cell lung cancer cells, estrogen receptor β increases MALAT1 gene transcription by binding the estrogen response elements at the MALAT1 gene promoter." (PMID 32174966, 2020). "Besides, there were studies also reporting that lncRNA Malat1 participated in proliferation, migration, and invasion in human hepatoma Hep3B 72 and non-small cell lung cancer cells 73 via sponging miR-200a." (PMID 32802189, 2020). "Also known as nuclear enrichment autosomal transcript 2 (NEAT2), MALAT1 was initially identified through subtractive hybridization as one of the transcripts most significantly over-expressed in metastatic non-small cell lung cancer tissues." (PMID 32174966, 2020). "Furthermore, lncRNA MALAT1 was highly expressed in non-small cell lung cancer cells while miR-124 was poorly expressed, and miR-124 was a direct target of MALAT1." (PMID 31775815, 2019). "As this SNP has been associated with a longer median survival time in non-small cell lung cancer patients than those without the SNP, it is possible that this SNP disrupts binding of miR-217-5p to MALAT1." (PMID 31717552, 2019). "MALAT1 was originally discovered to predict metastasis and survival of non-small cell lung cancer." (PMID 30093838, 2018). "MALAT1 was initially identified as a marker for early non-small cell lung cancer." (PMID 29435112, 2018).